NOD2 (nucleotide binding oligomerization domain containing 2)
Diseases named in the same sentence as NOD2 in open-access papers (continued):
Sharing a sentence is not in itself a finding about the gene and the disease.
cancer (continued). "However, the role of nucleotide-binding oligomerization domain 2 (NOD2) in cancer is not well understood." (PMID 35807169, 2022). "Recently, NOD2 had been connected to cancer development and treatment." (PMID 34268854, 2021). "To explore whether the depletion of NOD2 in TAMs was induced by cancer cells, we co‐cultured either HBEpiC or LUAD cells with THP‐1." (PMID 34268854, 2021). "Emerging evidence has been found between NOD2 and human cancers." (PMID 34925465, 2021). "Decreased NOD2 expression could be induced by cancer cells and lead to the phenotypic polarization of macrophages from protective M1 phenotype to pro‐tumorigenic M2 subtype which might be attributed to the down‐regulating of NF‐κB signalling pathway." (PMID 34268854, 2021). "NOD2 is an important component of the innate immune system and it constitutes an interesting regulatory target in terms of strengthening the immune response against cancer cells." (PMID 32144252, 2020). "With the development of research, we found that the NLRs family, including NOD1, NOD2 and others, may also play some role in the area of cancers." (PMID 29254180, 2017). "To determine whether a similar pattern of the effects of TNFα and CSE on NOD2 expression was seen in ileal biopsies we cultured biopsies obtained from otherwise healthy individuals undergoing cancer-screening endoscopy (n = 10) with CSE±TNFα." (PMID 21931826, 2011). "Our observation that MHCII+ monocytes expand in Notch2-deficient mice in steady-state conditions might also be in line with NOD2-dependent inducible monocytes and potentially open new treatment options by modulating monocyte Notch2 signaling in cancer patients." (PMID 41244563, 2025). "Although NOD2 is well known for its role in inflammatory responses, its role in cancer has been widely debated, with some suggesting that NOD2’s inflammatory response promotes cancer and others suggesting that it has anticancer effects based on data analysis of a number of genetic mutations." (PMID 36316517, 2023). "Also, as in many other types of cancer, NOD2 was downregulated in ccRCC to promote metastasis." (PMID 36248876, 2022). "The role of NOD2 in cancer is controversial and may depend on the type of cancer considered." (PMID 34208621, 2021). "However, how NOD2 contributes to the initiation and the progression of cancer remains ill defined." (PMID 25071785, 2014). "Taken together, the observations reported in Section 2.1 suggest that NOD2/RIPK2 can impinge on metabolic pathways and can be regulated by tumor suppressor genes, linking inflammation, cancer and metabolism." (PMID 40095546, 2025). "Our experimental results indicate that NOD2 influences cancer stemness properties in GBM cells, as evidenced by the reduced expression of CSC markers CD44 and CD133 following the NOD2 knockdown." (PMID 40868292, 2025). "NLRP3, NOD2, and NLRP1 were all highly expressed in primary tumors, further validating the protective role of PRGs in inhibiting cancer metastasis." (PMID 38697992, 2024). "Interestingly, our study found that V. parvula affects only Nod2 expression, mediating activation of NF-κB pathway signaling, which induces the expression of pro-inflammatory cytokines, chemokines, and adhesion molecules, to subsequently influence cancer progression." (PMID 37452162, 2023). "DPV-001 (DRibbles vaccine) is an off-the-shelf multivalent autophagosome-enriched cancer vaccine that contains > 300 putative cancer antigens, including alternative cancer neoantigens—cancer’s dark matter, DAMPS, HSPs and agonists for TLR 2, 4, 7, 8, and NOD2." (PMID 37507765, 2023). "The online GEPIA tool analysis TCGA database indicates that the expressions of Groα, NOD1, NOD2 and RIPK2 in the cancer sample (n=519) are higher than those of in the normal tissue (n=44)." (PMID 37151389, 2023). "AIM2 was differentially expressed in multiple cancers, including bladder, breast, esophageal, kidney, liver, lung, stomach, and endometrium, as well as CASP5, NOD2, and GZMB." (PMID 34906145, 2021).
cancer (continued). "In this study, we showed for the first time that NOD2 was an effective direct activator of AMPK pathway in HCC cells, which indicated its great potential for the manipulation of cancer." (PMID 32144252, 2020). "The purpose of this review is, therefore, to evaluate NOD receptors as new targets in cancer immunotherapy and to highlight the NOD1 and NOD2 agonists as well as antagonists reported to exhibit anticancer activity." (PMID 30548868, 2019). "NOD2-induced nonclassical monocytes are believed to develop in the absence of Notch2 signaling and mediate protection against cancer metastases." (PMID 41244563, 2025). "Given NOD2’s established role in cancer progression and the fundamental importance of the EMT and CSC in malignant behavior, we hypothesized that NOD2 may play a crucial role in GBM progression." (PMID 40868292, 2025). "Interestingly, our study also revealed hub genes (MEG3, MIAT, IRF1, ADAMTS9-AS2, TP63, NOD2, NOD1, NLRP3, MAGI2-AS3, and PVT1, respectively) within the pyroptosis-related ceRNA network, some of which have been well-studied in the field of cancer biology." (PMID 37511974, 2023). "In addition, according to the Cancer Cell Line Encyclopedia (CCLE) database, the expression levels of NOD1 and NOD2 in PC cell lines are generally very low." (PMID 35115556, 2022). "Although the roles of TLRs in the progression of liver injury and cancer are being actively investigated, it remains largely unknown whether activation of NOD1 and NOD2 is beneficial or harmful in these diseases." (PMID 36268029, 2022). "The result revealed that the expressions of NOD2, CASP1, IL6, and NLRP6 were negatively correlated with some or most drugs, while IL6 was also positively correlated with WZ3105 and MPS‐1‐IN‐1 in the cancer therapeutics response portal database." (PMID 35574984, 2022). "We chose to validate BIRC2 by qPCR because it is an upregulated member of the NOD2 pathway at a crossroads between growth, immunity, and cancer, yet BIRC2 has been reported to have no phenotype when knocked down in C. elegans." (PMID 27822466, 2016). "Moreover, ΔsagA showed increased antibiotic sensitivity, yielded lower levels of active muropeptides, displayed reduced activation of the peptidoglycan pattern-recognition receptor NOD2, and failed to promote cancer immunotherapy." (PMID 38857064, 2024).
inflammation (21 papers, 2010 to 2025). Aberrant reaction of the microcirculation characterized by movement of fluid and leukocytes from the blood into extravascular tissues. "Nod2 was the first susceptibility gene identified for Crohn’s disease, however, the functional role of Nod2 in the pathogenesis of intestinal inflammation remains unknown and the role of Nod2 in other inflammatory and non-inflammatory disorders is mostly unexplored." (PMID 28373658, 2017). "Functional studies show that VCP controlled ER stress induces inflammatory responses in a NOD2-dependent fashion; thus, providing a new potential mechanistic link and therapeutic target in NOD2-related intestinal inflammation." (PMID 35273242, 2022). "The immunological response occurring during periapical inflammation includes expression of nucleotide binding oligomerization domain containing 2 and hepcidin." (PMID 35764993, 2022). "In this regard, these cellular populations appear to be crucial in NOD2-related signals to exert a control on IAV-induced lung inflammation and in a chronic inflammatory environment." (PMID 29445379, 2018). "A more recent study has investigated the effect of Nod2 deletion in a spontaneous mouse model of chronic intestinal inflammation, SAMP1/YitFc, characterized by a progressive cobblestone CD-like ileitis that develops in the absence of chemical, genetic, or immunological manipulation." (PMID 29515999, 2018). "The Nod2 Nacht domain mutations are associated with eye, joint and skin, but not intestinal inflammation whereas the Crohn's-associated LRR domain polymorphisms are generally associated with intestinal, but not with extraintestinal, manifestations." (PMID 20531959, 2010). "Thus, we suggest that excessive activation of IL-23p19-mediated pro-inflammatory pathways due to NOD2 over-expression may be responsible for the occurrence of intestinal inflammation in IBD patients." (PMID 27563808, 2016). "It has been postulated that decreased NOD2 function manifests itself in a failure to respond to pathogens, facilitating invasion of bacteria and abnormal interaction between the gut mucosal immune system and luminal antigens, which culminate in chronic intestinal inflammation." (PMID 25071778, 2014). "Therefore, it appears that NOD2 plays a dual role in the pathogenesis of chronic intestinal inflammation, by protecting the intestinal mucosa under normal physiological conditions and inducing the production of pro-inflammatory cytokine during the chronic phase of gut inflammation." (PMID 25071778, 2014). "Our prior work demonstrated that lncRNA ITSN1-2 enhances NOD2/RIP2 signaling, promoting FLS proliferation and inhibiting apoptosis, thereby exacerbating synovial inflammation in RA." (PMID 40629453, 2025). "TLR4 and NOD2, as key PRRs, and their recognition of MAMP have been shown to be a key event in the development of mammary inflammation." (PMID 36204322, 2022). "NOD2 knockouts exhibited excessive intestinal inflammation as compared to NOD2 sufficient mice, and selective deletion of ATG16L1 in T cells ends with spontaneous intestinal inflammation, characterized by a decrease in Foxp3+ Tregs and aberrant expression of Th2 cells." (PMID 34440615, 2021).
metabolic disease (11 papers, 2015 to 2025). A congenital disorder (due to inherited enzyme abnormality) or acquired (due to failure of a metabolically important organ) disorder resulting from an abnormal metabolic process. "Increased expression of NOD2 has been documented in various human metabolic disorders and chronic diseases linked to mitochondrial dysfunction." (PMID 38755492, 2024). "While this study only looked at the impact of a combined loss of NOD1 and NOD2, further studies have examined the requirement of these two receptors individually in the development of metabolic disease." (PMID 33503814, 2021). "Overall, there is not currently strong evidence of a genetic link of either NOD1 or NOD2 polymorphisms and the development of human metabolic disease." (PMID 33503814, 2021). "Our results show that dietary factors (such a fat intake) and genetic determinants (such as NOD2 frame shift mutations) should be considered as factors that contribute to potential links between metabolic disease and IBD." (PMID 25666722, 2015). "Some studies of metabolic dysfunction using NOD1 and NOD2 deficient mice were conducted in germ-free mice, devoid of circulating peptidoglycan fragments, strongly supporting a role for circulating peptidoglycan in metabolic disease." (PMID 37128291, 2023). "In addition to their classical roles as bacterial sensors, NOD1 and NOD2 have been implicated as mediators of metabolic disease." (PMID 33503814, 2021). "More recently, NOD1 and NOD2 have been implicated as mediators of human metabolic disease." (PMID 33503814, 2021). "Although the roles of NOD1 and NOD2 in metabolic diseases have been elucidated to some extent through animal models, further investigations are warranted to unravel the precise underlying mechanisms." (PMID 39329913, 2024). "Based on the impaired metabolic function and more severe inflammation in the NOD2−/− mice the conclusion is that NOD2 signaling is protective against metabolic disease and this protection requires Rip2k signaling." (PMID 37128291, 2023). "Beside their functions as PRRs in antibacterial immune defense, NOD1 and NOD2 more recently have been reported to contribute to metabolic diseases, especially in the context of IR." (PMID 37239938, 2023). "This suggests that on balance the impact of NOD1 activation is a stronger influence on metabolic disease than the protective signals from NOD2." (PMID 37128291, 2023). "Additional evidence of a protective role for NOD2 in metabolic disease development is found in related mouse models of NAFLD." (PMID 33503814, 2021). "Although NOD1 and NOD2 share intracellular signaling pathway components, they are differentially upregulated on a cellular level and have opposing impacts on metabolic disease development in mouse models." (PMID 33503814, 2021). "One mechanism proposed to drive activation of NOD1 or NOD2 in metabolic disease is excess nutrients generated during overfeeding conditions acting as endogenous ligands or danger-associated molecular patterns (DAMPs) to stimulate inflammation." (PMID 33503814, 2021). "Overall, these studies highlight the cell type specific responses of NOD1 and NOD2 that modulate ROS production and mitochondrial dysfunction that may contribute to metabolic disease." (PMID 33503814, 2021). "Taken together, these studies link aberrant NOD1 and NOD2 expression and activation, rather than genetic variants, with metabolic diseases." (PMID 33503814, 2021). "Clinical studies have provided insight into whether NOD1 or NOD2 signaling is potentially altered in human metabolic disease." (PMID 33503814, 2021). "The activating stimuli for NOD1 and NOD2 in the context of metabolic disease is controversial and may be a combination of metabolic and bacterial ligands, as well as involve direct and indirect mechanisms of action." (PMID 33503814, 2021).
metabolic disease (continued). "The activating stimuli for NOD1 and NOD2 in the context of metabolic disease are controversial and may be a combination of both metabolic and circulating bacterial ligands." (PMID 33503814, 2021). "Taken together, these studies demonstrate that NOD1 activation may promote metabolic disease development, while the actions of NOD2 protect against the development of diet-induced metabolic disease in mouse models." (PMID 33503814, 2021). "Finally, many of the proposed roles for NOD1 and NOD2 in metabolic disease have been defined in animal models and require more extensive investigation in larger studies of human metabolic disease." (PMID 33503814, 2021). "In addition to NOD1 and NOD2, NLRP3 activation is linked to more severe metabolic disease and bacterial peptidoglycan is a known activator of NLRP3, but experiments directly testing the impact of peptidoglycan on NLRP3-induced metabolic changes have not been reported and will require further study." (PMID 37128291, 2023). "We recently showed that the microbial sensor NOD2 mediates the onset of metabolic diseases in mice; therefore, to assess whether this receptor may be involved in the regulation of the observed hepatic phenotype, we inoculated conventional NOD2 KO mice." (PMID 28302863, 2017). "Similarly, the nature of the NOD1 and NOD2 activating signals in the context of metabolic disease is yet to be conclusively defined with studies indicating the existence of circulating factors, which could be dietary or microbial (or a combination of both) that activate these NLRs." (PMID 33503814, 2021). "Evidence suggests that NOD1 and NOD2 play both positive and negative roles in ROS generation and subsequent mitochondrial dysfunction that may mediate the pathogenesis of metabolic disease." (PMID 33503814, 2021).
infectious disease (9 papers, 2016 to 2025). A disorder directly resulting from the presence and activity of a microbial, viral, or parasitic agent in humans. "It has been shown that the polymorphisms in the NOD2 gene contribute to failure in microbial detection and are associated with increased susceptibility to some infectious diseases and granulomatous inflammation." (PMID 34440800, 2021). "This functional dichotomy positions NOD2 as a promising therapeutic target for inflammatory and infectious diseases." (PMID 41017210, 2025). "This suggests pleiotropic effects of the NOD2 and LRRK2 variants across neurodegenerative, inflammatory and infectious diseases." (PMID 36972292, 2023). "The effect of heterozygous NOD2-2197AC pigs on disease resistance should be evaluated, and further investigations are expected to show the efficacy of the DNA marker on other infectious diseases." (PMID 34573406, 2021). "Despite its recognized potential as a therapeutic target for inflammatory and infectious disorders, critical gaps remain in our understanding of how to precisely calibrate the immunomodulatory effects of NOD2 across diverse genetic backgrounds, microenvironmental contexts, and disease paradigms." (PMID 41017210, 2025). "Given that genetic susceptibility to infectious diseases can be polygenic, we hypothesized that murine double knockout (DKO) of Mincle and Nod2 would result in exacerbation of altered immunity to mycobacterial infection leading to a more extreme phenotype than either KO alone." (PMID 35418999, 2022). "The contribution of NOD2 to UPR responses indicates the link between ER stress and innate immunity and provides a new avenue for therapeutic methods for treating inflammatory and infectious diseases." (PMID 34440800, 2021).
intestinal diseases (8 papers, 2016 to 2025). "Our findings suggest that genetic variants in NOD2 are only associated with OFG in patients with concurrent intestinal disease." (PMID 27306066, 2016). "Furthermore, it has been demonstrated that intestinal diseases can be transmitted to healthy mice by means of gut microorganisms, and the existence of an altered microbiota in patients with NOD2 deficiency has been found to promote the process." (PMID 38419631, 2024). "Although no monogenic intestinal diseases directly caused by NOD2 mutations have been identified, both AR and AD mutations in downstream regulators of the NOD2 cascade have been described." (PMID 40649913, 2025). "Likewise, nucleotide-binding oligomerization domain 2 (NOD2) is an important regulator of resistance to microbial invasion and maintenance of tissue homeostasis in intestinal diseases of the organism." (PMID 37021078, 2023). "Our results suggest that missense coding variation in NOD2 in patients with OFG may reflect the presence of intestinal disease." (PMID 27306066, 2016). "The association between cytoplasmic pattern recognition receptor nucleotide-binding oligomerization domain 2 (NOD2) and the pathogenesis of intestinal diseases has been established." (PMID 38419631, 2024). "Although no monogenic intestinal diseases have been directly linked to core autophagy genes, several monogenic disorders—including XIAP and NPC1 deficiencies—feature Crohn’s-like colitis and involve impaired NOD2-induced autophagy." (PMID 40649913, 2025).
neurodegenerative disease (4 papers, 2013 to 2022). A disorder of the central nervous system characterized by gradual and progressive loss of neural tissue and neurologic function. "All of which suggested that chronic inflammation mediated by possible abnormal NOD2 by the encoding variants might be involved in the etiology of neurodegenerative diseases." (PMID 29881342, 2018). "A recent study has found that ER stress can induce inflammation through Nod proteins, which could indicate a role of Nod2 signaling in neuroinflammation in neurodegenerative diseases." (PMID 27830463, 2017).
kidney diseases (2 papers, 2019 to 2024). "Collectively, the NOD2 and NLRC5 showed proinflammatory effects in some renal diseases, and our results revealed a potential association between the NLRs and the development of AAV." (PMID 31186034, 2019). "Previous studies, along with ours, have shown that inhibiting HuR significantly reduces NF-kB signaling, nucleotide-binding oligomerization domain 2 (NOD2) or IL-17-mediated inflammation, and Nox2- or Nox4-mediated oxidative stress in kidney diseases." (PMID 39273597, 2024).